PGR (progesterone receptor)
Diseases named in the same sentence as PGR in open-access papers (continued):
Sharing a sentence is not in itself a finding about the gene and the disease.
cancer (continued). "Currently, immunohistochemical assays that detect abundance of proteins are used to identify expression of estrogen receptor (ER), progesterone receptor (PR), and human epidermal growth factor receptor 2 (HER2) and determine the rate of proliferation of the cancer cells (Ki67)." (PMID 27896218, 2016). "There was no statistical difference in patient age, cancer grade, cancer stage, and expression of estrogen receptor/progesterone receptor among women of positive stomatin expression compared with those of negative stomatin expression." (PMID 27577936, 2016). "Thus, malignant tumors showed significantly lower ERα (ESR1) and PGR gene expression than normal mammary tissues (p = 0.017 and p = 0.002, respectively)." (PMID 26370564, 2015). "While TNBC represents a highly diverse group of cancers, it can be characterized by a lack of the estrogen receptor (ER) and progesterone receptor (PR) and by the absence of overexpression of the human epidermal growth factor receptor 2 (HER2)." (PMID 26673577, 2015). "In this study, we found that PABC shared many histological characteristics with non-PABC tumors except size, cancer stage, and progesterone receptor expression." (PMID 25415309, 2014). "The combined use of the two imaging examinations improved the sensitivity of screening regardless of ER or PgR status, but had a higher sensitivity in hormone receptor (ER and PgR) positive cancers than in those negative (90.0% vs. 63.2%, P = 0.03)." (PMID 23961381, 2013). "These clinical in situ lesions displayed the same immunophenotype (positive for CK5/6, CK14, CK17 and EGFR, and negative for Her2/neu and ER/PgR) as the invasive basal-like cancer component, suggesting a common precursor lesion." (PMID 23548208, 2013). "Clinical parameters such as tumor grade and age, along with biomarkers currently available such as estrogen receptor (ER) and progesterone receptor (PR) status, do not provide the information to fully understand and describe the complexity of cancer." (PMID 24688711, 2013). "They showed that Mifepristone is able to inhibit the growth of in vitro cancer cells derived from the nervous system, breast, prostate, ovary, and bone, with an absence of expression of classic nuclear progesterone receptor in nearly all these cells." (PMID 23530939, 2013). "All cases were negative for ER, and all but one HPV-negative carcinoma with squamous differentiation (H-score index: 30), were negative for PgR; 19 cases did not overexpress the HER2 receptor." (PMID 24083491, 2013). "Women who had ER-positive, PgR-positive, or GATA3-positive cancer were infrequently diagnosed first with lung metastases (20 (14.1%) of 142 vs. 21 (23.3%) of 90, P = 0.072; 13 (12.3%) of 106 vs. 29 (23.4%) of 124, P = 0.030; and 21 (13.9%) of 151 vs. 16 (23.5%) of 68, P = 0.079, respectively)." (PMID 21914172, 2011). "HER2-positive and ER- and PgR-negative cancers tended to give rise first to liver metastases more frequently compared with the other subtypes (in 13 (27.1%) of 48 vs. 44 (16.1%) of 273 first distant sites the site was in the liver, P = 0.067)." (PMID 21914172, 2011). "Claudin-low carcinomas are mostly triple-negative - negative for progesterone receptor (PR), estrogen receptor (ER), and epidermal growth factor receptor 2 (HER2) - and presumably originated from more primitive stem cells." (PMID 21952072, 2011). "Previously Caggiano and colleagues used data from the California Cancer Registry (CCR) to show that HER2 status did not differentiate survival among ER-negative/progesterone receptor (PR)-negative patient cases." (PMID 19228416, 2009). "The carcinomas of the patients in both surgical categories predominantly over expressed Her-2, and were mostly ER and PgR negative." (PMID 17892570, 2007).
cancer (continued). "Our results on BRCA2 cancers were quite similar to those of Palacios and colleagues and Lakhani and colleagues, although in the former study the BRCA2 cancers were more ER-positive and PgR-positive (on the basis of smaller sample set of 14 cases)." (PMID 15642173, 2005). "Tamoxifen therapy (40 mg d-1) did not influence the expression of PgR, EGFR or Ki67 immunostaining in cancer associated normal tissue (n = 17)." (PMID 1911227, 1991). "PgR negative cancers (n = 18), changed to positive in one case." (PMID 41511682, 2026). "Moreover, ERα and AR proteins increased, whereas ERβ and PGR diminished markedly in neoplastic relative to non-neoplastic colonic tissues, and the dysregulations were maximal in late-stage cancers in both genders." (PMID 37206439, 2023). "While the anti-cancer effects of E2 and P4 monotherapies were equal, their combination protocols showed boosted tumoricidal actions against CRC in males, possibly by promoting ERβ and PGR-mediated androgen deprivation together with inhibition of ERα-regulated oncogenic pathways." (PMID 36263327, 2022). "In breast cancer, estrogen receptor (ER), progesterone receptor (PR), and human epidermal growth factor receptor 2 (HER2) are currently considered a milestone in the clinical decision-making process, providing crucial information about prognosis, and predicting response to cancer treatments." (PMID 36158576, 2022). "At present, clinicians typically classify carcinomas into five subtypes (luminal A, luminal B HER2−, luminal B HER2+, HER2, and TN) on the basis of histologic and molecular characteristics, which notably include expression of the estrogen receptor (ER), progesterone receptor (PR), HER2, and Ki67." (PMID 35328381, 2022). "The enrichment of cancer cells with pluripotency features after treatments with 4OHT and fulvestrant in PDS cultures as depicted by gene expression analysis, was further supported by an increase in Sox2 protein levels, and a reduction in PgR and Ccna2 proteins levels." (PMID 34172801, 2021). "Of note, one patient had an ER and PgR negative, and an additional seven patients had ER and PgR unknown primary cancers." (PMID 34117261, 2021). "Triple negative breast cancers (TNBC) account for approximately 12% of breast cancers, and are defined as cancers that are hormone receptor negative, lacking significant expression of estrogen receptor (ER), progesterone receptor (PR) and human epidermal growth factor receptor (HER2)." (PMID 34681087, 2021). "This graph summarizes the impact of IAC on cancer incidence (14.0% vs. 47.3% p < 0.001) and multiplicity (0.18 vs. 0.85 cancers/rat, p < 0.0001), HIAC versus LIAC, respectively, as previously reported, as well as showing the mean percent progesterone receptor staining cells." (PMID 30917509, 2019). "Furthermore, EBCCs-c-KitR are related to a more indolent cancer behavior: high disease free survival, low grading, metastatic lymph nodes negative, receptor (ER, PgR, HER2neu) positive status." (PMID 29487702, 2018). "Another possibility is that rural patients with cancer may be more likely to have delays in chemotherapy administration, which can adversely affect survival in patients with estrogen receptor–negative, progesterone receptor–negative cancers in particular." (PMID 30646114, 2018). "However, cancer aromatase expression was independent of estrogen receptor (ER), progesterone receptor (PgR), and human epidermal growth factor receptor 2 statuses." (PMID 28489882, 2017). "In addition, the ER− breast cancer category is a combination of HER2+ cancers and triple negative (estrogen receptor negative, progesterone receptor negative and HER2 negative) cancers." (PMID 26874356, 2016). "Interestingly, even human cancer cells that lack of estrogen or progesterone receptor expression behave as hormonal responsive cells and secret human-specific milk proteins into the lumen of lactating hosts." (PMID 24709643, 2013).
cancer (continued). "In contrast, recent studies showed that Rab25 expression is decreased in human colon cancers and triple-negative (negative for estrogen receptor (ER), progesterone receptor (PR), and Her2/Neu) breast cancers, and Rab25 functions as a tumor suppressor in these cancers." (PMID 22121362, 2012). "Women who had ER-positive or PgR-positive cancer rarely had the brain as the first distant metastatic site compared with women whose cancer did not express these proteins (3 (2.1%) of 142 vs. 8 (8.9%) of 90, P = 0.025; 1 (0.9%) of 106 vs. 10 (8.1%) of 124, P = 0.012)." (PMID 21914172, 2011). "All cancers were required to be invasive node-negative, smaller than 2 cm in diameter and well or moderately differentiated, to contain no extensive intraductal component, to be progesterone receptor-positive, DNA diploid, have S-phase fraction ≤7 and be excised with at least 1 cm margin." (PMID 11161371, 2001). "Triple-negative breast cancer (TNBC) refers to breast cancer that is negative for estrogen receptor (ER), progesterone receptor (PR) and proto-oncogene HER-2 by immunohistochemical examination of cancer tissue." (PMID 38717531, 2024). "TNBC is characterized as progesterone receptor-negative (PR), estrogen receptor-negative (ER) and HER2-negative providing the name “triple-negative” to this subtype of cancer." (PMID 36765535, 2023). "Unlike other cancers, TNBC does not express progesterone receptor (PR), ER or HER2, and delivering effective targeted therapy for TNBC remains a challenge." (PMID 36096820, 2022). "TNBC presents molecular differences such as lacking expression of the estrogen receptor (ER), progesterone receptor (PR), and HER2 proteins, making this cancer have a poor clinical prognostic and lack clear strategies for its treatment." (PMID 36292927, 2022). "Progesterone receptor positive cancer tissues have higher levels of HOXD12 and D13 than negative cancer tissues in BRCA." (PMID 36213580, 2022). "The analysis revealed the highest upregulation of PGR and LINC01016 genes in ER+ compared to ER− cancers (regardless of HSF1 status)." (PMID 34783649, 2021). "TNBC, which defines the absence of staining for the estrogen receptor, progesterone receptor, and HER2, is an aggressive cancer with a poor survival rate regardless of stage." (PMID 31337063, 2019). "Nearly 80% or more of SNVs in FLT3, PDGFRA, PGR, and RET were not expressed among all cancer patients." (PMID 29721196, 2018). "In particular, increased BRIP1 transcript levels were found in tumors with an estrogen receptor-negative, progesterone receptor-negative or HER-2-positive status, in basal-like cancers and in stage 2 tumors as compared to stage 1 carcinomas." (PMID 28317894, 2017). "It is well known that negative results for oestrogen receptor (ER-), progesterone receptor (PR-), and HER2 (HER2-) expression in breast cancer cells signifies that the cancer is triple-negative cancer." (PMID 28220843, 2017). "Although MDA-MB-231 cells are triple-negative with the absence of expression of oestrogen receptor, progesterone receptor and HER2, LTV-BR and LTV-BR-RRR12 elicited similar anti-cancer activity as compared to MCF7 cells." (PMID 26734838, 2016). "Another cancer with a significant mortality rate is triple negative breast cancer (TNBC) that is negative for estrogen receptor (ER), progesterone receptor (PR) and human epidermal growth factor receptor-2 (Her-2)." (PMID 26848769, 2016).
cancer (continued). "By virtue of TNBC lacking estrogen receptor (ER), progesterone receptor (PR) and HER2 expression, there are no targeted biological therapies currently used as standard treatment for these cancers." (PMID 25658419, 2015). "BRCA1 tumors are typically estrogen receptor (ER) negative, progesterone receptor (PR) negative and HER2 negative (triple-negative) cancers, while the majority of BRCA2 tumors are ER positive and HER2 negative." (PMID 23704984, 2013). "TNBC is characterized by the absence of progesterone receptor (PR), estrogen receptor (ER), and human epidermal growth factor receptor 2 (HER-2) expression with a median overall survival (OS) rarely exceeding 12 to 18 months in advanced cancers." (PMID 40463869, 2025). "Other antibodies—ER, PgR, and HER2—are usually negative, similar to common metaplastic carcinomas." (PMID 41488090, 2025). "The results of immunohistochemistry showed the cancer cells were positive for CK7, estrogen receptor, progesterone receptor, and negative for CK20, villin, confirming the diagnosis of metastatic rectal adenocarcinoma originating from uterine endometrial adenocarcinoma." (PMID 37986305, 2023). "Moreover, no significant changes were observed for the BRCA oestrogen and BRCA progesterone receptor status, HER2/neu receptor, or menopause status of the cancers (data not shown here)." (PMID 34174910, 2021). "Next, we examined p97 expression in three mammary cell lines with progressive malignancy: the immortalized mammary epithelial MCF10A cells, luminal adenocarcinoma MCF-7 cells, and poorly differentiated, triple (estrogen receptor, progesterone receptor, and HER2) negative carcinoma MDA-MB-231 cells." (PMID 33731668, 2021). "With the exception of three clusters of NRs representing NR classes I (cluster I: RORC, VDR, PPARA, NR1D1, THRA, RORA, NR1H3; cluster II: RARB, PPARG, THRB) and III (cluster III: ESR1, PGR, AR, ESRRG), NR class was not a good determinate of NR expression patterns in the different cancer types." (PMID 32024906, 2020). "Malignant tumors with invasive growth of FFPE samples showed significantly lower gene expression of hormone receptors than tumors that were not invasive (ESR1 p = 0.014; PGR p = 0.033; PRLR p = 0.0006; GHR p = 0.011, respectively)." (PMID 27649560, 2016). "Moreover, SCCs are often triple-negative (TN) cancers, negative for the expression of the estrogen receptor (ER), progesterone receptor (PgR) and human epidermal growth factor receptor 2 (HER2) and certain ACs are TN cancers." (PMID 24520287, 2014). "MBCs tended to be high-grade (77%), triple negative (negative for estrogen receptor, progesterone receptor, and HER2) [27/33; 81.8%], and carcinomas with low incidence of axillary lymph node involvement (15%), and decreased disease-free [71% (95%CI: 54%, 94%) at 3 yrs)." (PMID 21110878, 2010). "Due to the absence of an estrogen receptor (ER), progesterone receptor (PR) and human epidermal growth factor receptor 2 (HER2), chemo-, immuno- and radiation therapy (RT) are the only effective treatments for this type of cancer, especially in combination for the treatment of stage I and II TNBCs." (PMID 35897841, 2022).
adenocarcinoma (19 papers, 2012 to 2025). A common cancer characterized by the presence of malignant glandular cells. "Imaging revealed diffuse bone metastases, and bone biopsy confirmed a poorly differentiated adenocarcinoma of breast origin (estrogen receptor, 60%; progesterone receptor, 35%; GATA3 positive)." (PMID 40666594, 2025). "A hysterectomy was performed and pathological examination identified a well-differentiated, estrogen receptor (ER)- and progesterone receptor (PR)-positive adenocarcinoma of the endometrium." (PMID 25624886, 2015). "It was shown that cytoplasmic estrogen receptor (ER)-α, cytoplasmic ER-β, and total progesterone receptor (PR) expression were higher in squamous cell carcinoma than in adenocarcinoma (AD), while HER2 expression was higher in adenocarcinoma than in squamous cell carcinoma." (PMID 37074188, 2023). "Furthermore PgR immunohistochemical reactivity was meaningfully recognized in adenocarcinoma (p=0.0002), appearing inversely related to TNM staging (p=0.0085)." (PMID 27690341, 2016). "For example, negativity for estrogen receptor (ER), progesterone receptor (PR), P16, and CD10, as well as positivity for carcinoembryonic antigen (CEA), diffuse p16, CD34, and HPV, suggests adenocarcinoma." (PMID 39465870, 2024). "MDA-MB-231 is a mesenchymal-stem-like BC adenocarcinoma cell line, characterized by the lack of expression of ER, PGR, and HER2 markers, which classifies it as a TNBC cell line." (PMID 36976215, 2023). "The histological analysis revealed a poorly differentiated adenocarcinoma, negative for estrogen receptor (ER), progesterone receptor (PgR), human epidermal growth factor receptor 2 (HER-2) and epidermal growth factor receptor (EGFR)." (PMID 29346284, 2018). "MCF-7 and LCC9 human adenocarcinoma cell lines are estrogen receptor (ER) and progesterone receptor (PR) positive but do not overexpress human epidermal growth factor receptor 2 (HER2)." (PMID 25909287, 2015). "We next decided to compare the effects of mercury between the “well-differentiated” adenocarcinoma Ishikawa cells and the “less-differentiated” Hec-1B cells (which do not express for example, estrogen receptor α and progesterone receptor)." (PMID 26600472, 2015). "Finally, it is important to emphasize that the present study was conducted on MCF7-derived cells, an estrogen receptor positive/progesterone receptor positive/human epidermal growth factor receptor-2 negative adenocarcinoma line derived from a metastatic site." (PMID 32733384, 2020).
infection (9 papers, 2010 to 2025). The state of being infected such as from the introduction of a foreign agent such as serum, vaccine, antigenic substance or organism. "Both the PDGF BB and PGR pathways are also predicted to be activated by infection of A549 cells with other molds, such as Rhizopus delemar and Rhizopus oryzae." (PMID 37255456, 2023). "We tested the relevance of PGR activation to infection by pretreating airway epithelial cells with an inhibitor of PGR activation, mifepristone." (PMID 37255456, 2023). "In addition to DEX activating GR, KLF15 can cooperate with the progesterone receptor and/or the androgen receptor to activate bovine herpesvirus (BoHV-1) immediate early gene expression, which enhances productive infection." (PMID 40872334, 2025). "In these models, preterm labor is caused either by inhibiting progesterone receptor (PR) activity and subsequently incurring premature progesterone withdrawal using RU486 (mifepristone), or by an infection-simulation inflammation pathway via lipopolysaccharide (LPS) injection in mice." (PMID 38635533, 2024). "The expression of the four cell proliferation/survival genes (C11ORF82, PGR, SOX11 and HELLS) are significantly reduced when C. burnetii's protein synthesis is inhibited during infection of THP-1 cells." (PMID 20854687, 2010). "We observed that neither a 10 fold increase in progesterone receptor nor a 2 fold increase in Cox 2 inhibition were effective in preventing the PRA/PRB increase at levels of NF-κB activation that might occur during subclinical infection." (PMID 20111699, 2010).
benign tumor (7 papers, 2015 to 2025). "Some studies have shown that the expression of the estrogen receptor (ER), progesterone receptor (PR) or both is more frequent in benign tumors and is generally associated with a favorable prognosis." (PMID 37835752, 2023).
gastrointestinal tumors (2 papers, 2020 to 2021). "Interestingly, a high correlation was observed among AR, ESR1, and PGR genes in gastrointestinal tumors (COAD, READ, and STAD) as they may play a synergistic role in these tumors." (PMID 32536040, 2020).